IGFBPL1 (insulin like growth factor binding protein like 1)
Description:
IGF-binding proteins prolong the half-life of IGFs and have been shown to either inhibit or stimulate the growth promoting effects of the IGFs in cell culture. They alter the interaction of IGFs with their cell surface receptors (By similarity). May be a putative tumor suppressor protein.
Synonyms: IGFBP-rP4; IGFBPRP4; bA113O24.1
Tractability: Antibody: UniProt places it where antibodies can reach, with high confidence; UniProt predicts a signal peptide or a membrane-spanning region; its Gene Ontology location is reachable by antibodies, with medium confidence.
Gene: Protein-coding gene on chromosome 9 (38,406,528 to 38,424,454, reverse strand). Ensembl gene ENSG00000137142.
Subcellular location: Secreted
Subcellular location (Human Protein Atlas): Nucleoplasm; Vesicles; Predicted to be secreted
Gene Ontology:
Molecular function: protein binding; receptor ligand activity; insulin-like growth factor binding
Biological process: cellular response to tumor cell; regulation of signal transduction; regulation of cell growth; signal transduction
Cellular component: extracellular region; non-collagenous component of interstitial matrix
Genetic constraint (gnomAD): Loss-of-function variants: 13 observed, 12.18 expected, observed/expected ratio (o/e) 1.07, 90% interval 0.69 to 1.67. The upper end of that interval is the gene's LOEUF score, 1.67, which puts it in group 6 of 6, group 1 being the genes least tolerant of losing a copy. Missense variants: 347 observed, 244.68 expected, observed/expected ratio (o/e) 1.42, 90% interval 1.3 to 1.55. Synonymous variants: 135 observed, 109.99 expected, observed/expected ratio (o/e) 1.23, 90% interval 1.07 to 1.42.
Homologues: Orthologues: chimpanzee IGFBPL1 (100% identical), macaque IGFBPL1 (94% identical), dog IGFBPL1 (83% identical), pig IGFBPL1 (80% identical), rabbit IGFBPL1 (79% identical), guinea pig IGFBPL1 (78% identical), mouse Igfbpl1 (76% identical), rat Igfbpl1 (75% identical), tropical clawed frog igfbpl1 (46% identical). Paralogues in human: IGFBP7 (41% identical), KAZALD1 (35% identical).
Diseases named in the same sentence as IGFBPL1 in open-access papers:
IGFBPL1 is named in the same sentence as 22 diseases in open-access papers, as found by Europe PMC text mining. Sharing a sentence is not in itself a finding about the gene and the disease. The quoted sentences say what the papers report.
breast carcinoma (7 papers, 2013 to 2025). "The inactivation of IGFBPL1 is associated with the pathogenesis of breast cancer; moreover, IGFBPL1 inhibits the growth of cancer cell by inhibiting the signaling pathway PI3K-AKT in esophageal cancer." (PMID 37088808, 2023). "Epigenetic silencing of IGFBPL1, a member of the insulin-like growth factor binding protein, is associated with nodal involvement and poorer outcome in breast cancer." (PMID 27633254, 2016). "IGFBPL1 was reported to play a role in neural development and notably, its expression is reduced in breast cancer, potentially due to aberrant hypermethylation of its promoter region." (PMID 41272850, 2025). "In breast cancer, the expression of IGFBPL1 is regulated by aberrant hypermethylation, implying that the down-regulation of IGFBPL1 is involved in the pathogenesis of this malignancy." (PMID 38157252, 2023). "The expression of IGFBPL1 was reduced in breast cancer, and its expression was regulated by promoter region methylation." (PMID 32041673, 2020). "The IGFBPL1 gene was reported to be frequently methylated in human breast cancer and regulated by promoter region methylation, and methylation of IGFBPL1 was associated with poor prognosis." (PMID 32041673, 2020). "The rs7018644 SNP at the 9p13.1 locus in the intronic region of IGFBPL1 was associated with non-dense area and was the only variant in our GWAS that showed consistent replication in both Asian breast cancer cases and the validation study in women of European ancestry." (PMID 41272850, 2025).
esophageal cancer (3 papers, 2020 to 2023). A primary or metastatic malignant neoplasm involving the esophagus. "In esophageal cancer, IGFBPL1 suppressed human esophageal cancer cell xenografts growth in mice by inhibiting esophageal cancer cell proliferation and inducing cell apoptosis." (PMID 38157252, 2023). "Methylation of IGFBPL1 is a potential esophageal cancer early detection marker and a predictive marker for PI3K-targeted therapy in ESCC." (PMID 32041673, 2020). "Further study found that IGFBPL1 suppresses esophageal cancer cell growth both in vitro and in vivo." (PMID 32041673, 2020). "To further understand the mechanism of IGFBPL1 in esophageal cancer development, we studied the role of IGFBPL1 in PI3K-AKT signaling in esophageal cancer cells." (PMID 32041673, 2020). "Taken together, these results suggested that the expression of IGFBPL1 is regulated by promoter region methylation in esophageal cancer cells." (PMID 32041673, 2020). "IGFBPL1 suppresses esophageal cancer cell growth by inhibiting PI3K-AKT signaling in vitro and in vivo." (PMID 32041673, 2020). "IGFBPL1 inhibited esophageal cancer cell clonal formation and proliferation and induced cell apoptosis and G1/S phase arrest." (PMID 32041673, 2020). "In this study, we found that the expression of IGFBPL1 is regulated by promoter region methylation in human esophageal cancer." (PMID 32041673, 2020). "Methylation of IGFBPL1 is associated with tumor size and TNM stage and therefore may serve as an esophageal cancer early detection marker." (PMID 32041673, 2020). "IGFBPL1 expression was detected by semi-quantitative RT-PCR in esophageal cancer cell lines." (PMID 32041673, 2020). "The expression and function of IGFBPL1 in esophageal cancer remain to be elucidated." (PMID 32041673, 2020). "IGFBPL1 is a novel tumor suppressor in human esophageal cancer." (PMID 32041673, 2020). "Then, we analyzed the effect of IGFBPL1 on PI3K-AKT pathway in esophageal cancer." (PMID 32041673, 2020). "The function and mechanism of IGFBPL1 in esophageal cancer remains to be elucidated." (PMID 32041673, 2020). "Our results demonstrate that IGFBPL1 inhibited PI3K-AKT signaling in human esophageal cancer cells." (PMID 32041673, 2020).
glaucoma (2 papers, 2022 to 2025). Increased pressure in the eyeball due to obstruction of the outflow of aqueous humor. "Likewise, intravitreal administration of insulin-like growth factor binding protein like-1 (IGFBPL1), which acts by binding to IGF-1, was able to slow visual decline in a microbead-induced mouse model of glaucoma." (PMID 35251042, 2022).
atherosclerosis (1 paper, 2023). A disease characterized by the build-up of fatty material and calcium deposition in the arterial wall resulting in partial or complete occlusion of the arterial lumen. "In this study, our results showed that the expression of IGFBPL1 was down regulated in unstable atherosclerosis plaque and lipid-laden macrophages." (PMID 38157252, 2023). "Through the Gene Expression Omnibus (GEO) database analysis, we found that IGFBPL1 was the top 10 down-regulated gene in unstable atherosclerosis plaque." (PMID 38157252, 2023). "Our results provide a theoretical basis of IGFBPL1 in the alternative or adjunct treatment options for atherosclerosis by reducing lipid accumulation in macrophages." (PMID 38157252, 2023). "The top 20 differently expressed genes from GSE97210 showed that IGFBPL1 was decreased in unstable atherosclerosis plaque." (PMID 38157252, 2023). "Our results provide a theoretical basis of IGFBPL1 in anti-atherosclerosis therapy by reducing lipid accumulation in macrophages." (PMID 38157252, 2023). "Thus, this study will clarify the effect and mechanism of IGFBPL1 on the lipid accumulation in macrophages and provide a theoretical basis of IGFBPL1 in the treatment for atherosclerosis." (PMID 38157252, 2023). "However, there is no published paper about the mechanism of IGFBPL1 in atherosclerosis progress and macrophage lipid accumulation." (PMID 38157252, 2023). "However, there is no published article reporting the function of IGFBPL1 on lipid accumulation in macrophages and atherosclerosis." (PMID 38157252, 2023). "Moreover, our results also showed that IGFBPL1 inhibits macrophage lipid accumulation by enhancing the activation of IGR-1R/LXRα/ABCG1 pathway, suggesting that targeting IGFBPL1 may be an effective therapy for atherosclerosis." (PMID 38157252, 2023).
autism (1 paper, 2024). Persistent deficits in social interaction and communication and interaction as well as a markedly restricted repertoire of activity and interest as well as repetitive patterns of behavior. "Similarly, IGFBPL1, with almost 2-fold greater expression in astrocytes vs. neurons, was a gene with >30-fold reduced expression in the astrocytes of patients with autism (p = 0.04) but was not significantly different in neurons." (PMID 38994948, 2024).
esophageal squamous cell carcinoma (1 paper, 2020). Esophageal squamous cell carcinoma (ESCC) is a type of esophageal carcinoma (EC) that can affect any part of the esophagus, but is usually located in the upper or middle third. "IGFBPL1 was methylated in 47.3% (53/114) of esophageal dysplasia and 49.1% (246/501) of human primary esophageal squamous cell carcinoma (ESCC)." (PMID 32041673, 2020).
glioblastoma (1 paper, 2021). The most malignant astrocytic tumor (WHO grade IV). "However, MGH57 (grade IV glioblastoma) revealed a relatively small subpopulation of malignant cells that do not express OLIG1, OLIG2, DLL1, CCND1, and IGFBPL1, but express ALDOC and ATP1A2." (PMID 33607293, 2021).
kidney cancer (1 paper, 2023). Primary or metastatic malignant neoplasm involving the kidney. "Among them, IGFBP2, IGFBP3, IGFBP4, IGFBP6 and IGFBP7 showed higher expression levels, especially in gastric, liver and lung cancer cell lines; conversely, IGFBP1, IGFBP5 and IGFBPL1 showed relatively lower expression, particularly in colorectal, gastric and kidney cancer cell lines." (PMID 37088808, 2023).
myeloma (1 paper, 2018). "Bacterially produced IGF-1 was co-immunoprecipitated (co-IPed) with recombinant IGFBPL1, which was purified from a mouse myeloma cell line." (PMID 29391597, 2018).
prostate carcinoma (1 paper, 2017). A carcinoma that arises from epithelial cells of the prostate gland. "Another intronic SNP in ALDH1B1 (also close to IGFBPL1) was found to be associated with increased mortality following a diagnosis of low‐grade prostate cancer." (PMID 27643404, 2017).
synucleinopathy (1 paper, 2024). A neurodegenerative disease that is characterized by the abnormal accumulation of aggregates of alpha-synuclein protein in neurons, nerve fibers or glial cells. "Even though the neuroprotective potential of IGFBPL1 has to be further verified in synucleinopathy models, this protein could represent a novel molecular target against α-synuclein-induced neuroinflammation." (PMID 38378800, 2024).
tumor (7 papers, 2013 to 2024). "Methylation of IGFBPL1 is associated with tumor size and TNM stage." (PMID 32041673, 2020). "The mean tumor volume was 189.53 ± 18.42 mm3 and 90.54 ± 17.29 mm3 in IGFBPL1 unexpressed and re-expressed KYSE150 cell xenografts, respectively." (PMID 32041673, 2020). "The tumor weight decreased significantly in IGFBPL1 re-expressed KYSE150 cell xenografts (t test, p < 0.001)." (PMID 32041673, 2020). "Methylation of IGFBPL1 was significantly associated with TNM stage (p = 0.012), and tumor size (p = 0.009)." (PMID 32041673, 2020). "The tumor weight was 265.58 ± 46.86 mg vs. 83.08 ± 18.12 mg in IGFBPL1 unexpressed and re-expressed KYSE150 cell xenografts." (PMID 32041673, 2020). "Other IGF family members with increased RNA message levels in this tumor (compared to muscle and bone) include IGFBPL1 (5-6-log2-fold), IGFL3 (6-7-log2-fold), and IGF2BP3 (2-6-log2-fold)." (PMID 25861239, 2015). "Furthermore, overexpression of FGF12, FGF14, FGF17, FGFR1, FGFBP3 and IGFBPL1 genes was found in early tumor stage, while, overexpression of IGF1R, IGF2BP2 and INSRR was found in advanced tumor stages." (PMID 34061869, 2021).
cancer (6 papers, 2011 to 2023). A tumor composed of atypical neoplastic, often pleomorphic cells that invade other tissues. "We also detected increased expression of Igfbpl1, another gene associated with cancer cell proliferation." (PMID 23533150, 2013). "Relatively speaking, IGFBP4, IGFBP7 and IGFBPL1 showed more amplifications of copy number in multiple cancer types." (PMID 37088808, 2023). "IGFBPL1 was highly expressed in the paired paracancerous tissues, while expression was reduced in cancer tissues (p < 0.001)." (PMID 32041673, 2020). "The Cancer Genome Atlas (TCGA) database was employed to predict whether the expression of IGFBPL1 is regulated by promoter region methylation." (PMID 32041673, 2020). "Supporting this is the identification of multiple genes downregulated in poor prognosis patients that are reported to be epigenetically silenced in cancer, such as SYNM and IGFBPL1." (PMID 27633254, 2016).
IGFBPL1 also shares sentences with these, for which no sentence is quoted: amyloidosis (1 paper); depression (1); leiomyoma (1); liver cancer (1); lung carcinoma (1); lymph node metastasis (1); major depression (1); neurodegenerative disease (1); Obesity (1).